CLEC7A (C-type lectin domain containing 7A)
Diseases named in the same sentence as CLEC7A in open-access papers (continued):
Sharing a sentence is not in itself a finding about the gene and the disease.
Alzheimer disease (8 papers, 2020 to 2025). A progressive, neurodegenerative disease characterized by loss of function and death of nerve cells in several areas of the brain leading to loss of cognitive function such as memory and language. "Clec7a expression is previously reported as a feature of DAM during Alzheimer disease, and in our studies the kinetics Clec7a expression by microglia is well correlated with the clinical course of EAE." (PMID 36980209, 2023). "In the Alzheimer’s disease 5xFAD mouse model, where Gal3 deletion was reported to lower amyloid plaque burden, the absence of Gal3 does not affect microgliosis but elevates Clec7a levels around plaques." (PMID 41487996, 2025). "To assess the CAM state, we measured Clec7a/Dectin1 levels in cultured microglia because Clec7a defines the CAM state but is also increased in response to diverse disease states, including animal models of Alzheimer’s disease, multiple sclerosis, amyotrophic lateral sclerosis, and aging." (PMID 36514132, 2022).
Autoimmunity (8 papers, 2009 to 2022). The occurrence of an immune reaction against the organism's own cells or tissues. "In line with the immunosuppressive phenotype induced by Dectin-1, Clec7a-/- mice showed aged-related symptoms of autoimmunity and enhanced immune responses against apoptotic cells-derived antigens." (PMID 35237264, 2022).
allergic asthma (7 papers, 2018 to 2026). A asthma with a basis in a pathological type I hypersensitivity reaction. "Single nucleotide polymorphisms in the genes encoding the fungal recognition receptors CLEC7A and mannose-binding lectin have been associated with susceptibility to allergic asthma." (PMID 41438035, 2025). "Already a few SNPs have been identified in human dectin-1 gene (CLEC7A) which correlates with development of allergic asthma, highlighting the importance of this receptor in driving allergic asthma." (PMID 29696023, 2018). "Moreover, single nucleotide polymorphisms in the genes encoding the fungal recognition receptors dectin-1 (CLEC7A) and mannose-binding lectin (MBL2) have been associated with allergic asthma susceptibility." (PMID 34060330, 2021).
breast carcinoma (7 papers, 2008 to 2025). "High CLEC7A expression has been linked to poor survival in breast cancer." (PMID 35783358, 2022).
chronic mucocutaneous candidiasis (7 papers, 2011 to 2021). "In addition, deleterious mutations in multiple direct or downstream immune effectors, notably CLEC7A, STAT3, and CARD9, have been found in human cohorts with high prevalence of chronic mucocutaneous candidiasis (CMC) and have been recapitulated and studied in mice." (PMID 21533108, 2011).
amyloid (6 papers, 2020 to 2025). "More specifically, our collective studies demonstrated that activating the SYK‐associated receptor CLEC7A via injection with either anti‐CLEC7A antibodies or a natural, fungal‐derived CLEC7A ligand both offer effective interventions to limit amyloidosis in 5xFAD mice." (PMID 36629045, 2023). "When amyloid and HHcy co-occur, there may be both an increase in Clec7a mRNA across the wider microglial population, as well as an increase in the proportion of microglia that are plaque-associated (due to the enhanced amyloid burden)." (PMID 32943069, 2020). "Finally, constitutive deletion of Rev‐erbα in the 5XFAD model of AD decreased amyloid plaque number and size and prevented plaque‐associated increases in disease‐associated microglia markers including TREM2, CD45, and Clec7a." (PMID 31800167, 2020). "Because amyloid plaque deposition is associated with the accumulation of disease‐associated microglia (DAM), we examined expression of the DAM markers Trem2, Clec7a, and CD45 within the cortex of 5XFAD/RKO compared with the 5XFAD." (PMID 31800167, 2020). "We did not observe the downregulation of homeostatic genes in AD groups, and while TREM2, CLEC7A and CTSD were indeed overexpressed in the presence of amyloidosis, only TREM2 and CTSD upregulation seemed to be specific of FAAH deletion in pathological conditions." (PMID 34587978, 2021).
colon cancer (6 papers, 2017 to 2024). "Next, we examined gene expression by RNA-seq analysis in colonic tumors and non-tumor tissues from AOM-3DSS-treated GF mice, as we could detect the difference between WT and Clec7a−/− mice more clearly than using SPF mice." (PMID 36932082, 2023).
colorectal cancer (6 papers, 2022 to 2024). A primary or metastatic malignant neoplasm that affects the colon or rectum. "A positive correlation was also observed between CLEC7A expression levels and colorectal cancer disease stages." (PMID 36932082, 2023). "Furthermore, in patients with colorectal cancer (CRC), the expression of CLEC7A is also observed in MDSCs and correlated with the death rate and tumor severity." (PMID 36932082, 2023).
onychomycosis (6 papers, 2014 to 2022). "CLEC7A-Y238X, an early stop codon variant that impacts recognition of fungal β-glucan by the receptor Dectin-1, was reported in a Dutch family where all were affected by onychomycosis." (PMID 32185141, 2020). "A study identified and explained a CLEC7A nsSNP i.e., Y238X (rs16910526) in antifungal defenses in onychomycosis and RVVC." (PMID 31555269, 2019). "For example, a few DECTIN-1–deficient patients who carry the p.Y238* CLEC7A mutation in homozygosity, which abolishes DECTIN-1–dependent signaling, were reported to develop recurrent VVC (RVVC) and onychomycosis." (PMID 34964702, 2022).
paracoccidioidomycosis (6 papers, 2014 to 2023). A systemic fungal infection caused by Paracoccidioides brasiliensis that is most often seen in immunocompromised patients. "Therefore, our research indicates that the CLEC7A and PROM1 genes are important for the cytokine response induced by P. brasiliensis and may influence the Paracoccidioidomycosis disease outcome." (PMID 37108883, 2023).
Influenza infection (5 papers, 2012 to 2025). "Influenza infection significantly decreased mRNA level of macrophage receptors CLEC7A, MSR1, CD36, and MRC1." (PMID 22396727, 2012). "A decrease of CLEC7A in infected AM suggests that these cells might not efficiently recognize and engulf fungi after influenza infection." (PMID 22396727, 2012).
lung carcinoma (5 papers, 2022 to 2025). "So far, little is known regarding the relationship between CLEC7A and lung cancer." (PMID 35480896, 2022). "Similar with the bioinformatics results in TCGA database, our experiments confirmed the expression of CLEC7A, TLR7, IL-1A and IL33 were decreased in lung cancer." (PMID 37259066, 2023).
lupus (5 papers, 2014 to 2025). "Upregulation of Axl, Clec7a, Itgax, Ccl5, and Cxcl10 was also observed in NZB/NZW mice, indicating common lupus pathology." (PMID 31888754, 2019).
Stroke (5 papers, 2020 to 2025). Sudden impairment of blood flow to a part of the brain due to occlusion or rupture of an artery to the brain. "Genes related to cell proliferation (Top2A, Mki67, and Stmn1) and those affiliated with disease-associated microglia (DAM) such as Apoe, Cst7, Clec7a, Lyz2, Lgals3bp, Igf1, and Lpl are prominently expressed during the acute and subacute phases of stroke." (PMID 39633897, 2024). "In mice, knockout of microglial Clec7a decreases the engulfment of synapses, increases the number of synapses, and thereby significantly mitigates stroke‐induced neurological deficits." (PMID 39088351, 2024). "In this study, we identified a functional role for Clec7a in microglial synaptic phagocytosis, which may have broader implications for understanding the neurological mechanisms underlying synaptic vulnerability in stroke and other neurological disorders characterized by synaptic dysfunction." (PMID 39088351, 2024). "Genes linked to microglial responses to demyelination, Alzheimer’s disease, and stroke, including Apoe, Lpl, Spp1, Clec7a, and Cst7, are also upregulated." (PMID 39633897, 2024). "Interestingly, Clec7a has been reported to be involved in the inflammatory response following not only AD, but also TBI and stroke, all being pathological conditions associated with rod microglia." (PMID 37341831, 2023). "The interaction between Clec7a and MD2 drives microglia-mediated synaptic phagocytosis, exacerbating post-stroke neurological deficits." (PMID 40723833, 2025).
viral infections (5 papers, 2010 to 2024). "Furthermore, 28 patients had viral infections, 19 of whom carried either CLEC7A or PLCG2 variants, compared with 9 without variants (n = 19 of 34 vs. 9 of 33; P = 0.0258, Fisher’s exact test)." (PMID 36166305, 2022).
gastric cancer (4 papers, 2017 to 2025). A primary or metastatic malignant neoplasm involving the stomach. "Furthermore, results from Protein Atlas database validate immune molecules including CD86, CD209, C3AR1, CLEC4D, CLEC7A and CYSLTR2 are positive in gastric cancer cells." (PMID 29152078, 2017).
glioma (4 papers, 2015 to 2025). A benign or malignant brain and spinal cord tumor that arises from glial cells (astrocytes, oligodendrocytes, ependymal cells). "The results unequivocally demonstrate that within glioma tissues, CLEC7A is predominantly expressed on tumor-associated macrophages." (PMID 38846954, 2024). "To validate the association between CLEC7A expression and macrophages and microglia in gliomas, we analyzed single-cell data from the CGGAS database and the GEO database (GSE70630, GSE84465, GSE89567)." (PMID 38846954, 2024). "Subsequently, we conducted both univariate and multivariate Cox regression analyses using data from the CCGA and TCGA database, revealing CLEC7A expression as an independent risk factor for gliomas." (PMID 38846954, 2024). "The result established a significant correlation, demonstrating that high expression of CLEC7A was associated with reduced OS among glioma patients." (PMID 38846954, 2024). "To elucidate the specific impact of CLEC7A on macrophages, we conducted correlation analyses to explore the relationship between CLEC7A and genes associated with glioma chemotaxis and polarization in publicly available databases." (PMID 38846954, 2024). "To further the immune cells most associated with CLEC7A in glioma tissues, we applied CIBERSORT to classify and analyze the proportion of 22 immune cells retrieved from the TCGA and CGGA databases." (PMID 38846954, 2024). "Consequently, we can infer a strong correlation between tumor-associated macrophages and CLEC7A expression within the glioma immune microenvironment." (PMID 38846954, 2024). "The findings from enrichment analysis suggest that CLEC7A may be associated with immune infiltration in gliomas." (PMID 38846954, 2024). "CLEC7A expression is intricately linked to the pathology and molecular characteristics of gliomas, establishing its role as an independent prognostic factor for gliomas and influencing macrophage function." (PMID 38846954, 2024). "Furthermore, the expression of Clec7a was unchanged in glioma-associated macrophages/monocytes when compared to naïve monocytes." (PMID 25658639, 2015). "In the GL261 model a significant higher expression of all selected genes could be confirmed in glioma-associated macrophages/monocytes and for Il1rn, Clec7a, and Cxcr4 in glioma-associated microglia, compared to the respective control cells." (PMID 25658639, 2015). "Patients with high CLEC7A expression have worse prognosis, and CLEC7A is an independent prognostic factor for gliomas." (PMID 38846954, 2024). "Yet, the specific role of CLEC7A in gliomas and its impact on tumor immune responses remain inadequately elucidated." (PMID 38846954, 2024). "In conclusion, our findings strongly suggest that CLEC7A is highly expressed in M2 macrophages in glioma tissues." (PMID 38846954, 2024). "CLEC7A demonstrated a strong positive correlation with these inhibitory immune checkpoints, which contribute to suppressing the immune response in gliomas." (PMID 38846954, 2024). "Previous research has demonstrated the pivotal role of CLEC7A in the progression of various cancers, yet its specific implications within gliomas remain elusive." (PMID 38846954, 2024). "Glioma patients with high CLEC7A expression exhibited elevated immune, stromal, ESTIMATE scores and lower tumor purity." (PMID 38846954, 2024). "Examination of TCGA-derived samples uncovered a notable increase in the proportion of CD4 memory-activated T cells, M1 macrophages, and M2 macrophages within the CLEC7A high-expression cohort of glioma patients." (PMID 38846954, 2024). "Subsequently, a Transwell assay was conducted to demonstrate the impact of CLEC7A on the chemotaxis of M2 macrophages towards glioma cells." (PMID 38846954, 2024). "To summarize, our findings robustly support the involvement of CLEC7A in multiple aspects of immune responses within the glioma microenvironment." (PMID 38846954, 2024).
glioma (continued). "Conducting these experiments is vital to assess the potential efficacy of CLEC7A inhibitors in preclinical glioma studies, offering a foundation for innovative immunotherapeutic strategies to enhance patient prognosis." (PMID 38846954, 2024). "The expression of CLEC7A is upregulated in gliomas, and its levels escalate with the malignancy of tumors, establishing it as an independent prognostic factor." (PMID 38846954, 2024). "The findings disclosed a heightened expression of CLEC7A in glioma tissues, and its expression escalated with the tumor grade, aligning with the results in the database." (PMID 38846954, 2024). "This study employed bioinformatics and clinicopathological techniques to comprehensively evaluate the mRNA and protein expression levels of CLEC7A in gliomas." (PMID 38846954, 2024). "To robustly validate this observation, we utilized a receiver operating characteristic curve analysis for CLEC7A expression and its correlation with the mesenchymal subtype across gliomas of all grades." (PMID 38846954, 2024). "To predict the impact of CLEC7A on M2 macrophages in gliomas, we knocked out CLEC7A in M2 macrophages." (PMID 38846954, 2024). "Within the TCGA database, CLEC7A demonstrated elevated expression in samples of high-grade gliomas, MGMT un-methylated status, IDH wildtype status, and those 1p/19q no-codel status." (PMID 38846954, 2024). "This investigation involved examining and validating the relationship between CLEC7A and glioma using samples from Hospital, along with data from TCGA, GEO, GTEx, and CGGA datasets." (PMID 38846954, 2024). "To further validate the significance of CLEC7A in glioma immune reactions, we conducted GSVA to investigate its association with various immune processes." (PMID 38846954, 2024). "In our examination of the molecular expression profile of CLEC7A, we conducted an analysis of its distribution across distinct molecular subtypes of glioma within the TCGA database." (PMID 38846954, 2024). "To investigate the relationship between CLEC7A and gliomas, we first performed expression and survival analysis based on data from different databases and clinical patient information." (PMID 38846954, 2024). "The role of CLEC7A in glioma-induced immunosuppression is inferred from bioinformatics analysis, highlighting the need for functional experiments to understand its dysregulation fully." (PMID 38846954, 2024). "The primary objective of this study was to investigate the prognostic significance and immune therapeutic potential of CLEC7A in gliomas through the integration of bioinformatics and clinical pathological analyses." (PMID 38846954, 2024). "This information provides insights into the cellular localization of CLEC7A, which is crucial for understanding its interactions and potential functions in the context of gliomas." (PMID 38846954, 2024). "The results showed that CLEC7A expression is increased in gliomas, and its expression levels are correlated with WHO grades." (PMID 38846954, 2024). "Our investigation revealed a positive correlation between the expression of CLEC7A and monocyte chemoattractant factors (CCL2, CCL5) as well as factors implicated in M2 macrophage polarization (TGF-β1, CSF-1) in glioma samples obtained from both TCGA and CGGA databases." (PMID 38846954, 2024). "Given its immunomodulatory function, we hypothesize that CLEC7A may be a potential immune checkpoint in gliomas." (PMID 38846954, 2024). "Our investigation delved deeper into the prognostic significance of CLEC7A in glioma." (PMID 38846954, 2024). "Consequently, CLEC7A potentially contributes to the clinical progression of gliomas by influencing the immune system." (PMID 38846954, 2024). "Additionally, we investigated the potential mechanisms through which CLEC7A regulates the immunosuppressive microenvironment of gliomas." (PMID 38846954, 2024). "Subsequently, we assessed the prognostic significance of CLEC7A overexpression in glioma patients." (PMID 38846954, 2024).
glioma (continued). "The analysis unveiled a notable enrichment of CLEC7A expression in glioma samples." (PMID 38846954, 2024). "In addition, a significant increase in CLEC7A+ CD163+ cells was observed with increasing WHO grade of glioma." (PMID 38846954, 2024). "Therefore, we posit that CLEC7A may play a role in the processes of macrophage chemotaxis and polarization in gliomas." (PMID 38846954, 2024). "Therefore, a comprehensive exploration of the mechanistic role of CLEC7A in gliomas could pave the way for the identification of novel therapeutic interventions to counteract this formidable malignancy." (PMID 38846954, 2024). "Moreover, CLEC7A exhibits a significant elevation in mesenchymal subtype gliomas, which are distinguished by heightened immunosuppression, increased aggressiveness, and malignant proliferation driven by mesenchymal differentiation resulting from mutations in the NF1 gene." (PMID 38846954, 2024). "To explore the involvement of CLEC7A in gliomas, we conducted an analysis of CLEC7A expression levels in both non-tumor brain tissue and glioma samples utilizing data from TCGA, GTEx, and GEO (GEO50161) dataset." (PMID 38846954, 2024).
parasitic infections (4 papers, 2016 to 2025). "CARD9 is a critical adapter of C‐type lectin receptors (CLRs), such as Dectin‐1 (Clec7a), Dectin‐2 (Clec6a) and Mincle (Clec4e), in response to fungal, viral, bacterial and parasitic infections." (PMID 39118286, 2024).